CHRM4 (cholinergic receptor muscarinic 4)
Description:
The muscarinic acetylcholine receptor mediates various cellular responses, including inhibition of adenylate cyclase, breakdown of phosphoinositides and modulation of potassium channels through the action of G proteins. Primary transducing effect is inhibition of adenylate cyclase.
Synonyms: HM4; M4R
Tractability: Small molecule: an approved drug acts on it; a structure with a bound ligand is known; a high-quality ligand is known; it belongs to a druggable protein family. Antibody: its Gene Ontology location is reachable by antibodies, with high confidence; UniProt places it where antibodies can reach, with medium confidence; UniProt predicts a signal peptide or a membrane-spanning region. PROTAC: a small molecule that binds it is known.
Target class: Small molecule receptor (family A GPCR); Acetylcholine receptor; Monoamine receptor; Family A G protein-coupled receptor; Membrane receptor
Chemical probes: CHEMBL402207, Emraclidine (high quality), ML173, ML253, ML293, PCS1055 (high quality), PD 102807, VU0152100
Safety:
Unwanted effects reported when the protein is acted on. In parentheses: how it was acted on, where the effect was seen, and who reports it.
blurred vision (activation, acute dosing; nervous system, cardiovascular; source: Lynch et al. (2017))
catalepsy (activation, acute dosing; nervous system, cardiovascular; source: Lynch et al. (2017))
decreased blood pressure (activation, acute dosing; nervous system, cardiovascular; source: Lynch et al. (2017))
decreased heart rate (activation, acute dosing; nervous system, cardiovascular; source: Lynch et al. (2017))
decreased pupil diameter (activation, acute dosing; nervous system, cardiovascular; source: Lynch et al. (2017))
exhaustion (activation, acute dosing; nervous system, cardiovascular; source: Lynch et al. (2017))
frothing (activation, acute dosing; nervous system, cardiovascular; source: Lynch et al. (2017))
increased salivation (activation, acute dosing; nervous system, cardiovascular; source: Lynch et al. (2017))
irritability (activation, acute dosing; nervous system, cardiovascular; source: Lynch et al. (2017))
lacrimation (activation, acute dosing; nervous system, cardiovascular; source: Lynch et al. (2017))
muscle cramps (activation, acute dosing; nervous system, cardiovascular; source: Lynch et al. (2017))
ptosis (activation, acute dosing; nervous system, cardiovascular; source: Lynch et al. (2017))
sweating (activation, acute dosing; nervous system, cardiovascular; source: Lynch et al. (2017))
Gene: Protein-coding gene on chromosome 11 (46,383,589 to 46,391,990, reverse strand). Ensembl gene ENSG00000180720.
Subcellular location: Cell membrane; Postsynaptic cell membrane
Subcellular location (Human Protein Atlas): Golgi apparatus; Nucleoplasm; Plasma membrane; Primary cilium; Primary cilium tip
Pathways (Reactome):
Signal Transduction: G alpha (i) signalling events; Muscarinic acetylcholine receptors
Gene Ontology:
Molecular function: protein binding; G protein-coupled acetylcholine receptor activity; G protein-coupled receptor activity
Biological process: adenylate cyclase-inhibiting G protein-coupled acetylcholine receptor signaling pathway; cell surface receptor signaling pathway; chemical synaptic transmission; G protein-coupled acetylcholine receptor signaling pathway; G protein-coupled receptor signaling pathway, coupled to cyclic nucleotide second messenger; signal transduction; G protein-coupled receptor signaling pathway; regulation of locomotion
Cellular component: plasma membrane; dendrite; synapse; membrane; postsynaptic membrane
Genetic constraint (gnomAD): Loss-of-function variants: 5 observed, 26.4 expected, observed/expected ratio (o/e) 0.19, 90% interval 0.098 to 0.4. The upper end of that interval is the gene's LOEUF score, 0.4, which puts it in group 1 of 6, group 1 being the genes least tolerant of losing a copy. Missense variants: 402 observed, 671.27 expected, observed/expected ratio (o/e) 0.6, 90% interval 0.55 to 0.65. Synonymous variants: 290 observed, 288.03 expected, observed/expected ratio (o/e) 1.01, 90% interval 0.91 to 1.11.
Homologues: Orthologues: chimpanzee CHRM4 (100% identical), macaque CHRM4 (99% identical), dog CHRM4 (98% identical), rabbit CHRM4 (98% identical), pig CHRM4 (97% identical), guinea pig CHRM4 (96% identical), mouse Chrm4 (96% identical), rat Chrm4 (96% identical), tropical clawed frog chrm4 (73% identical), zebrafish chrm4a (72% identical). Paralogues in human: CHRM2 (58% identical), CHRM3 (45% identical), CHRM5 (42% identical), CHRM1 (41% identical), HRH1 (24% identical), DRD3 (22% identical), DRD4 (22% identical), HRH3 (22% identical), HTR1A (21% identical), DRD5 (21% identical), HTR1D (20% identical), DRD1 (20% identical), and 13 more.
Diseases named in the same sentence as CHRM4 in open-access papers:
CHRM4 is named in the same sentence as 34 diseases in open-access papers, as found by Europe PMC text mining. Sharing a sentence is not in itself a finding about the gene and the disease. The quoted sentences say what the papers report.
schizophrenia (12 papers, 2012 to 2024). A major psychotic disorder characterized by abnormalities in the perception or expression of reality. "Chromosome 11p11 also harbours genes that have been previously associated with schizophrenia and/or brain structural phenotypes, including CHRM4, MDK, AMBRA1 and HARBI127,66,67." (PMID 38016951, 2023). "The reduction in hippocampal CHRM4 mRNA levels in schizophrenia suggests this loss of binding reflects a loss of CHRM4 protein expression." (PMID 23805071, 2013). "On the other hand, CHRM4 encodes the muscarinic acetylcholine receptor M4, which has been proposed as a therapeutic target for schizophrenia, Therefore, conservation of rhythms in CHRM4 across species may be important for successful translation of these drugs into humans." (PMID 39872996, 2024). "There may also be a role for the CHRM4 gene as a susceptibility gene for schizophrenia, as it has been reported that the C/C allele at the 1341 single nucleotide polymorphism carries an increased risk for schizophrenia that is resistant to treatment with current drugs." (PMID 36909280, 2023). "There are also agonists or activators for products of six DEGs that are down-regulated in ASD (Lrrk2), schizophrenia (Chrm4, Prkca), schizophrenia and BP (Klf2) or schizophrenia, BP and MDD (Nr4a1 and Nr4a3)." (PMID 39502833, 2024). "Taken together, data from postmortem CNS show there are lower levels of CHRM1/CHRM4 in some people with schizophrenia." (PMID 36909280, 2023). "Here, because of the focus on schizophrenia, we will review the data pertinent to CHRM1 and CHRM4 as these are now implicated in the molecular pathology and treatment of the disorder." (PMID 36909280, 2023). "This is therefore a biological basis for the suggestion that specifically activating the CHRM4 would be a mechanism to reduce the psychotic symptoms of schizophrenia." (PMID 36909280, 2023). "In this study, those with the schizophrenia had approximately a 2.5-fold lower level of CHRM1/CHRM4 in the frontal, striatal, temporal, and occipital cortex compared to controls." (PMID 36909280, 2023). "This study added to an earlier study using 123I-IDEX SPECT that reported lower levels of CHRM1/CHRM4 in people with schizophrenia who were being treated with risperidone." (PMID 36909280, 2023). "The initial neuroimaging study of CHRMs in schizophrenia used 123I-IQNB SPECT to show there were lower levels of CHRM1/CHRM4 (30% in the striatum and 20% in frontal and temporal regions) in the CNS of drug-free people with the disorder compared to matched control subjects." (PMID 36909280, 2023). "More recent research has attempted to address some of the limitations of the early studies on CHRMs in schizophrenia by measuring CHRM1/CHRM4 using SPECT and 123I-IDEX binding in 30 medication-free people who were diagnosed with a psychotic disorder and were in the early phase of the disease." (PMID 36909280, 2023). "However, there is contrasting data relating to the role of CHRM4 in schizophrenia." (PMID 23805071, 2013). "In schizophrenia, subjects with deficits in CHRM1 protein expression also show a reduction in cortical and subcortical binding of [3H]AF-DX 384, a CHRM2/CHRM4 selective radioligand." (PMID 23805071, 2013). "Although both studies support lower levels of CHRM1/CHRM4 in people with schizophrenia, neither of the studies were sufficiently powered to identify the MRDS subgroup identified using postmortem CNS." (PMID 36909280, 2023). "These trials included phase II and III trials showing the efficacy of KarXT, which is predicted to having its therapeutic benefits from the inclusion of CHRM1/CHRM4 dual agonism, against the positive and negative symptoms of schizophrenia." (PMID 36909280, 2023). "Importantly, biperiden is a selective CHRM1/CHRM4 antagonist (10-fold more selective for CHRM1 over CHRM4) that is known to induce significant deficits in learning and memory in both patients with schizophrenia and controls." (PMID 36909280, 2023).
schizophrenia (continued). "Current data suggests that levels of CHRM4 are not altered in the prefrontal cortex or parietal cortex of people with schizophrenia." (PMID 36909280, 2023). "Moreover, neither study quantified CHRM1/CHRM4 in the hippocampus, a region important in modulating learning and memory which have shown impairments in people with schizophrenia." (PMID 36909280, 2023). "Hence, this review will focus on the data supporting a role for the CHRM1 and CHRM4 in the molecular pathology of schizophrenia and the physiological processes that are affected by the changes in CHRM1 and CHRM4 signaling that would be postulated to be occurring in people with the disorder." (PMID 36909280, 2023). "However, with the recognition that the breakdown of biochemical homeostasis in people with schizophrenia extends beyond the CNS some consideration should be given as to whether CHRM1 / CHRM4-mediated biochemical abnormalities in people with the disorder could extend beyond the CNS." (PMID 36909280, 2023). "Moreover, early data from the trial of treating schizophrenia with emraclidine indicate selectively targeting the CHRM4 may also be a mechanism to reduce psychotic and negative symptom severity." (PMID 36909280, 2023). "One of these studies also reported lower levels CHRM4, but not CHRM1, mRNA across the hippocampus from people with schizophrenia compared to controls." (PMID 36909280, 2023). "This hypothesis has gained support from a recent trial that has reported that the CHRM4 positive allosteric modulator (PAM), emraclidine, reduces the severity of both acute psychotic and acute negative symptoms in people with schizophrenia." (PMID 36909280, 2023). "In addition, the recent report that emraclidine, a specific CHRM4 PAM, lessons psychotic and negative symptoms in people with schizophrenia." (PMID 36909280, 2023).
prostate carcinoma (4 papers, 2021 to 2025). A carcinoma that arises from epithelial cells of the prostate gland. "To understand how CHRM4 expression is involved in microenvironmental variables, we examined the association between CHRM4 and cytokine responsiveness in prostate cancer using TCGA prostate cancer datasets." (PMID 37142586, 2023). "In this study, we demonstrated an association between AR inhibition and increased CHRM4 expression in various prostate cancer cell lines and clinical datasets." (PMID 37142586, 2023). "CHRM4 overexpression may drive neuroendocrine differentiation of prostate cancer cells and is associated with immunosuppressive cytokine responses in the tumor microenvironment (TME) of prostate cancer." (PMID 37142586, 2023). "We demonstrated that IFNA17 overexpression might enhance functional characteristics, such as migration, proliferation, and association with elevated levels of CHRM4, NE markers, and immune checkpoints in prostate cancer cells." (PMID 37142586, 2023). "Next, we assessed the role of CHRM4 in prostate cancer cells and found that CHRM4-overexpressing C4-2 cells exhibited increased rates of cell migration and invasion through Matrigel." (PMID 37142586, 2023). "Abundant CHRM4-driven AKT/MYCN signaling upregulates interferon alpha 17 (IFNA17) cytokine activity in prostate cancer after ADT." (PMID 37142586, 2023). "In summary, we found that ADT-induced IFNA17 expression positively affected the elevation of NED and immune checkpoint abundances in prostate cancer cells, which was dependent on CHRM4." (PMID 37142586, 2023). "Mechanistically, CHRM4-driven AKT/MYCN signaling upregulated the interferon alpha 17 (IFNA17) cytokine in the prostate cancer TME after ADT." (PMID 37142586, 2023). "In this study, we found that ADT resulted in loss of the tumor suppressor effect of AR and reduced binding of AR to the CHRM4 regulatory sequence, thereby enhancing CHRM4 expression in prostate cancer cells." (PMID 37142586, 2023). "After the screening, we selected a CHRM4 candidate inhibitor, ceritinib, to test its pharmacological effects on prostate cancer cells compared to known CHRM4 inhibitors (LY2033298 and PD102807)." (PMID 37142586, 2023). "We found that increased IFNA17 protein expression was associated with induction of CHRM4, phosphorylated (p)-AKT, and MYCN proteins in prostate cancer cells, but decreased expression of these proteins was observed after DHT treatment." (PMID 37142586, 2023). "We conducted a molecular docking analysis and in-house drug screening to study the promising therapeutic inhibitory effects of approved drugs targeting CHRM4 in prostate cancer." (PMID 37142586, 2023). "We sought to determine the role of CHRM4 in prostate cancer after ADT and its effect on cytokine responsiveness in the TME for NEPC differentiation." (PMID 37142586, 2023). "Next, we analyzed CHRM4 expression in prostate cancer cell lines and observed increased CHRM4 protein levels in PC3 and C4-2-MDVR cells." (PMID 33398073, 2021). "In our study, we established a link between NGF promotion of neuroendocrine differentiation via CHRM4 after the development of resistance to ADT in prostate cancer." (PMID 33398073, 2021). "The mean expression correlation was analyzed in prostate cancer datasets, which showed that CHRM4 was positively correlated with NGF, ZBTB46, and neuroendocrine marker expressions and inversely correlated with androgen-responsive gene expressions." (PMID 33398073, 2021). "In our previous study, we found that stimulation of the muscarinic acetylcholine receptor 4 (CHRM4)/AKT/MYCN pathway may lead to the development of NEPC in prostate cancer after ADT." (PMID 37142586, 2023). "Analysis of CHRM4-driven IFNA17 cytokine release in the prostate cancer TME following ADT resistance may provide a clear understanding of the feedback loop consisting of CHRM4/AKT/MYCN in the context of AR inhibition." (PMID 37142586, 2023).
prostate carcinoma (continued). "We found increased abundances of CHRM4 in high-grade tumors and small-cell prostate cancer (SCPC) samples, suggesting that CHRM4 may serve as a biomarker for predicting advanced prostate cancer." (PMID 37142586, 2023). "CHRM4 was highly expressed in prostate cancer cells after androgen-deprivation therapy (ADT)." (PMID 37142586, 2023). "In addition to NTRK1 and the NGFR, we identified a mechanism which is involved in ADT-mediated neuroendocrine differentiation in prostate cancer via CHRM4 upregulation." (PMID 33398073, 2021). "In addition, it was found that NGF participates in the neuroendocrine differentiation of prostate cancer since the inhibition or knockdown of NGF prevents neuroendocrine differentiation through a mechanism dependent on the cholinergic muscarinic receptor 4 (CHRM4)." (PMID 40243726, 2025). "Moreover, tissues expressing high CHRM4 levels were significantly correlated with downregulated AR-responsive gene signatures (GO, Wang, Nelson, PID, and Hallmark), as revealed by a gene set enrichment analysis (GSEA) in The Cancer Genome Atlas (TCGA) prostate cancer dataset." (PMID 37142586, 2023). "MYCN-driven PDL1 was significantly elevated when prostate cancer cells were cultured under ADT conditions or with IFNA17 treatment, and its expression decreased after CHRM4-KD." (PMID 37142586, 2023). "IFNA17 mediates a feedback mechanism in the TME by activating the CHRM4/AKT/MYCN signaling-driven immune checkpoint pathway and neuroendocrine differentiation of prostate cancer cells." (PMID 37142586, 2023). "We found a correlation between CHRM4 and IFNA17 cytokine response signaling in the TME of prostate cancer, in which abundant IFNA17 was found in prostate cancer cells cocultured with CM collected from M2-type TAMs." (PMID 37142586, 2023). "Positive correlations between CHRM4 and IFNA17 at the messenger (m)RNA and protein levels, functional characteristics, and clinical datasets were found in advanced and NEPC-like prostate cancers." (PMID 37142586, 2023). "We demonstrated the abundance of the IFNA17 protein in CHRM4-overexpressing cells and the serum of patients with metastatic prostate cancer, suggesting that IFNA17 is a potential prognostic marker for advanced prostate cancer." (PMID 37142586, 2023). "Thus, we discovered a mechanism of prostate cancer lineage plasticity that provides an effective prediction strategy utilizing gene expression-based biomarkers for NEPC development through the association of activated ZBTB46 and accumulated NGF via stimulation of the CHRM4–AKT–MYCN pathway." (PMID 33398073, 2021). "They show that NGF interacts with the GPCR CHRM4, that both NGF and CHRM4 are upregulated in highly metastatic prostate cancer and that targeting NGF reduces therapy resistance in a mouse xenograft model." (PMID 33398073, 2021). "Additionally, in an analysis of prostate cancer datasets (GSE21032 and TCGA), CHRM4 overexpression was positively correlated with an NEPC-response gene signature." (PMID 37142586, 2023). "We demonstrated that CHRM4/IFNA17-activated prostate cancer cells might interact with M2-type TAMs to promote NED and immune checkpoint pathways in prostate cancer cells, contributing to the development of an immunosuppressive TME and NEPC." (PMID 37142586, 2023). "Since there are no small molecules or inhibitors known to treat NEPC, we discovered that targeting CHRM4 using Food and Drug Administration (FDA)-approved small compounds may inhibit tumor growth and NED in prostate cancer cells in vitro and in vivo." (PMID 37142586, 2023). "In summary, IFNA17 cytokine secretion may be positively correlated with CHRM4 abundance, and may be involved in NED progression in advanced prostate cancer." (PMID 37142586, 2023).
prostate carcinoma (continued). "Our findings suggest that ADT-induced CHRM4 may activate AKT/MYCN signaling to induce IFNA17 secretion and upregulate immune checkpoints in the TME to drive potential immunosuppressive responses, leading to NED and metastasis in prostate cancer." (PMID 37142586, 2023). "AR expression in normal prostate tissues may inhibit CHRM4 expression; however, AR inhibition in advanced prostate cancer after ADT may lead to CHRM4/AKT/MYCN activation, which in turn promotes the NED and invasiveness of prostate cancer cells." (PMID 37142586, 2023).
Alzheimer disease (3 papers, 2013 to 2022). A progressive, neurodegenerative disease characterized by loss of function and death of nerve cells in several areas of the brain leading to loss of cognitive function such as memory and language. "Interestingly, elucidating the role of the cholinergic system in the etiology of psychosis has been aided by studies into Alzheimer's disease where the CHRM1/CHRM4 partial agonist Xanomeline can reduce psychotic symptoms." (PMID 23805071, 2013). "Post-mortem studies have also reported reduced binding of the radioligand [3H]4-DAMP, under CHRM1/CHRM3/CHRM4/CHRM5 selective assay conditions, in the orbitofrontal cortex from subjects with Alzheimer's disease who had significant psychotic symptoms." (PMID 23805071, 2013).